NDUFB6 (NADH:ubiquinone oxidoreductase subunit B6)
Description:
Accessory subunit of the mitochondrial membrane respiratory chain NADH dehydrogenase (Complex I), that is believed not to be involved in catalysis. Complex I functions in the transfer of electrons from NADH to the respiratory chain. The immediate electron acceptor for the enzyme is believed to be ubiquinone.
Synonyms: B17; CI
Tractability: Small molecule: an approved drug acts on it; a structure with a bound ligand is known. Antibody: UniProt predicts a signal peptide or a membrane-spanning region. PROTAC: ubiquitination databases record sites on it; its protein half-life has been measured.
Target class: Enzyme; Oxidoreductase
Gene: Protein-coding gene on chromosome 9 (32,553,001 to 32,573,184, reverse strand). Ensembl gene ENSG00000165264.
Subcellular location: Mitochondrion inner membrane
Subcellular location (Human Protein Atlas): Mitochondria; Nucleoplasm
Pathways (Reactome):
Metabolism: Complex I biogenesis; Respiratory electron transport
Metabolism of proteins: Mitochondrial protein degradation
Gene Ontology:
Molecular function: protein binding; NADH dehydrogenase (ubiquinone) activity
Biological process: mitochondrial ATP synthesis coupled electron transport; aerobic respiration; mitochondrial electron transport, NADH to ubiquinone; proton motive force-driven mitochondrial ATP synthesis; proton transmembrane transport
Cellular component: mitochondrial inner membrane; mitochondrial membrane; mitochondrion; respiratory chain complex I
Genetic constraint (gnomAD): Loss-of-function variants: 11 observed, 7.45 expected, observed/expected ratio (o/e) 1.48, 90% interval 0.9 to 1.92. That is too few expected variants to judge how well the gene tolerates losing a copy. Missense variants: 76 observed, 71.22 expected, observed/expected ratio (o/e) 1.07, 90% interval 0.89 to 1.29. Synonymous variants: 34 observed, 29.93 expected, observed/expected ratio (o/e) 1.14, 90% interval 0.86 to 1.51.
Homologues: Orthologues: chimpanzee NDUFB6 (100% identical), dog NDUFB6 (77% identical), guinea pig NDUFB6 (77% identical), pig NDUFB6 (77% identical), mouse Ndufb6 (70% identical), tropical clawed frog ndufb6 (66% identical), rabbit NDUFB6 (60% identical), rat Ndufb6 (59% identical), zebrafish ndufb6 (55% identical).
Diseases named in the same sentence as NDUFB6 in open-access papers:
NDUFB6 is named in the same sentence as 58 diseases in open-access papers, as found by Europe PMC text mining. Sharing a sentence is not in itself a finding about the gene and the disease. The quoted sentences say what the papers report.
gastric cancer (3 papers, 2018 to 2022). A primary or metastatic malignant neoplasm involving the stomach. "In gastric cancer, it was also proved that the expression of TOPORS-AS1 and its associated gene, NDUFB6 in gastric cancer tissues were significantly lower than that in adjacent tissues." (PMID 36313727, 2022). "Moreover, NDUFB6 expression was associated with the invasion and distal metastasis of gastric cancer." (PMID 29992774, 2018). "Since NDUFB6 is one member of the metabolic‐associated lncRNAs–mRNAs coexpression network, the results from our studies indicate that this network may contribute to gastric cancer development." (PMID 29992774, 2018). "The expression of TOPORS‐AS1 and its associated gene, NDUFB6 in gastric cancer tissues was significantly lower than that in adjacent nontumor tissues." (PMID 29992774, 2018). "These mean that NDUFB6 may be used as a biomarker of metastasis for patients with gastric cancer." (PMID 29992774, 2018).
Insulin resistance (3 papers, 2010 to 2021). Increased resistance towards insulin, that is, diminished effectiveness of insulin in reducing blood glucose levels. "Silencing Ndufb6 in myotubes reduced mitochondrial respiration and prevented rescue from palmitate-induced insulin resistance after EPS." (PMID 34659107, 2021).
type 2 diabetes (3 papers, 2010 to 2021). "Similarly, CpG-SNPs that create a CpG in the promoter region of the NDUFB6 gene can be methylated, leading to suppression of gene expression and increasing the susceptibility to type 2 diabetes." (PMID 26148682, 2015). "The NDUFB6 rs540467 SNP modifies PA-mediated changes in insulin sensitivity, body composition and liver fat estimates in type 2 diabetes." (PMID 34659107, 2021). "We previously demonstrated that an SNP in the NADH dehydrogenase-1ß subcomplex subunit 6 (NDUFB6) of the mitochondrial complex I relates to impaired muscle mitochondrial plasticity after exercise training in first-degree relatives of type 2 diabetic patients." (PMID 34659107, 2021).
cardiomyopathy (2 papers, 2019 to 2025). A disease of the heart muscle or myocardium proper. "Chord mapping revealed core genes (e.g., NDUFB6, RPL15, ATP5PB) involved in multiple interconnected pathways.DO analysis confirmed enrichment in cardiomyopathy, coronary artery disease, and myocardial infarction, supporting the cardiovascular specificity of the identified genes." (PMID 41200169, 2025).
clear cell renal cell carcinomas (2 papers, 2015 to 2018). "Clinical study has indicated that downregulation of NDUFB6 was implicated in poor prognosis of clear cell renal cell carcinomas." (PMID 29992774, 2018). "A recent study showed that NDUFB6 is a possible tumor suppressor of metastatic clear cell renal cell carcinomas." (PMID 29992774, 2018).
depression (2 papers, 2019 to 2021). "The expressions of Atp6v1f, Arpc5, Ndufb6, and Psmc6 were significantly down-regulated while Adcyap1r1 was up-regulated in the depression-susceptible group compared with the control group." (PMID 33737865, 2021). "The results indicated that Atp6v1f, Arpc5, Adcyap1r1, Ndufb6, and Psmc6 were distinctly dysregulated in the hypothalamus of the depression-susceptible group, while Gys1, Pgp, Klc1, Chka, Ncstn, Ndufa6, and Kyat1 were distinctly dysregulated in the anxiety-susceptible group." (PMID 33737865, 2021).
diabetes (2 papers, 2010 to 2023). "NDUFB6, a respiratory chain component related to insulin sensitivity, is decreased in skeletal muscle of patients with diabetes." (PMID 36864020, 2023).
ischemia (2 papers, 2018 to 2021). A hypoperfusion of the BLOOD through an organ or tissue caused by a PATHOLOGIC CONSTRICTION or obstruction of its BLOOD VESSELS, or an absence of BLOOD CIRCULATION. "Decreases in the activity of complex I in vehicle-treated mice subjected to ischemia were accompanied by reductions in the protein levels of subunits NDUFA9 (to 78% of sham) and NDUFS3 (to 82% of sham), but not NDUFB6." (PMID 34884479, 2021).
melanoma (2 papers, 2024 to 2025). A malignant, usually aggressive tumor composed of atypical, neoplastic melanocytes. "LONP1 over-expression results in impaired complex I assembly in melanoma cells, upregulation of NDUFB6,8,10 and 11, and downregulation of NDUFV1, NDUFV2, NDUFS3 and NDUFS7." (PMID 38263327, 2024).
renal cell carcinoma (2 papers, 2019 to 2026). "Mutations in NDUFB6 have been observed in oncocytic thyroid tumor and downregulation of NDUFB6 due to the loss in 9p24.1-p13.3 is known to be responsible for metastasis in renal cell carcinoma." (PMID 31338326, 2019).
endometrial cancer (1 paper, 2019). Primary or metastatic malignant neoplasm involving the endometrium (mucous membrane that lines the endometrial cavity). "One of the genes found to be associated with endometrial cancer, NDUFB6, was also found to be significantly associated with survival." (PMID 31338326, 2019). "The second most significant gene found to be associated with endometrial cancer in this study, NDUFB6 is a nuclear-encoded subunit of NADH-ubiquinone oxidoreductase, also known as Complex I (CI), which is the largest complex of the electron transport chain in mitochondria." (PMID 31338326, 2019). "Seven genes, including RBM12, NDUFB6, ATP6V1A, RECK, SLC35E1, RFX3 (Bonferroni-corrected P < 0.05) and ATP8A1 (suggestive P < 10−5), and one long non-coding RNA, DLGAP4-AS1 (Bonferroni-corrected P < 0.05), were associated with endometrial cancer." (PMID 31338326, 2019). "Out of 472 endometrial cancer patients, 74 had rare variants in NDUFB6, and they had a lower survival rate in comparison to endometrial cancer patients with no rare variants in NDUFB6." (PMID 31338326, 2019). "The survival analysis performed in this study also showed endometrial cancer patients with rare variants in NDUFB6 have a significantly lower survival rate than endometrial cancer patients with no rare variants reemphasizing its possible role in endometrial cancer." (PMID 31338326, 2019).
hepatoma (1 paper, 2020). "To test this possibility, we measured the levels of ATP and the abundance of proteins CYCS, NDUFB6, and UQCRB in Hepa1–6 cells (mouse hepatoma cells)." (PMID 32546794, 2020).
metastatic tumors (1 paper, 2015). "Therefore, we supposed that downregulation of NDUFB6 is implicated in cell proliferation in metastatic tumors." (PMID 25315157, 2015).
infection (15 papers, 2011 to 2025). The state of being infected such as from the introduction of a foreign agent such as serum, vaccine, antigenic substance or organism. "Finally, NDUFB6, involved in the mitochondrial respiratory chain complex, was down-regulated during in vitro FL13 infection and in most of the in vivo infected cells (macrophages and cDC subtypes) but showed the opposite pattern in Lena (data not shown)." (PMID 33365028, 2020). "Moreover, genes involved in active metabolism like COX7A2, NDUFB6 (ILC2), NDUFA12 (ILCP), ACSL1 (NK CD16high), and DNAJA4 (NK CD56high) were upregulated in HIV-infected children, suggesting active metabolism in these subsets in response to infection." (PMID 32937142, 2020).
cancer (10 papers, 2018 to 2026). A tumor composed of atypical neoplastic, often pleomorphic cells that invade other tissues. "Three variants in RBM12, one variant in NDUFB6, ten variants in DLGAP4-AS1, five variants in ATPV1A, eleven variants in RECK, four variants in SLC35E1, eight variants in RFX3, and eight variants in ATP8A1 were known somatically acquired mutations in various cancers." (PMID 31338326, 2019).
tumor (8 papers, 2013 to 2025). "On the basis of our present data, we propose that NDUFB6 is a possible tumor suppressor of metastatic ccRCCs." (PMID 25315157, 2015).
neurodegenerative disease (5 papers, 2021 to 2026). A disorder of the central nervous system characterized by gradual and progressive loss of neural tissue and neurologic function. "Ultimately, the temporal dynamics of the expression profiles of genes associated with neurodegenerative diseases, such as Ndufa2, Ndufb6, Snca, Ndufb8 and Cox8a, were characterized by trending." (PMID 37834317, 2023).
mitochondrial disease (4 papers, 2017 to 2025). "Many mitochondrial disease-related altered proteins also formed part of the energy network (DLD, NDUFA4, NDUFB5, NDUFB6, NDUFB9, NDUFS1, NDUFA12 and UQCRB) and belong to respiratory electron transport with the exception of DLD, which belongs to the TCA cycle." (PMID 34576238, 2021).
NDUFB6 also shares sentences with these, for which no sentence is quoted: Parkinson (5 papers); Leigh syndrome (4); Alzheimer disease (3); Leber hereditary optic neuropathy (3); renal oncocytomas (3); autoimmune disease (2); breast carcinoma (2); Hepatic steatosis (2); myopathies (2); Anxiety (1); Arthritis (1); autosomal dominant optic atrophy (1); benign tumors of the kidney (1); brain ischemia (1); chronic lymphocytic leukemia (1); Cirrhosis (1); colon cancer (1); colorectal cancer (1); colorectal tumors (1); coronary artery disease (1); dengue (1); developmental delay (1); encephalomyopathies (1); Encephalopathy (1); hematological disease (1); Huntington disease (1); myocardial infarction (1); non-alcoholic steatohepatitis (1); Obesity (1); oncocytoma (1).
A further 10 diseases each share a sentence with NDUFB6 in 1 paper.